ALB (albumin)
Diseases named in the same sentence as ALB in open-access papers (continued):
Sharing a sentence is not in itself a finding about the gene and the disease.
Hypoalbuminemia (continued). "When analyzing albumin as a categorical variable also in a multivariable model, hypoalbuminemia had nearly a threefold increase in the odds of FTR (OR 2.99, [95% CI 1.67–5.33]; p < 0.001) compared to normal albumin level (reference group)." (PMID 41228270, 2025). "Hypoalbuminemia was also more severe in deceased patients, with albumin levels consistently around 25 g/L, compared to stable levels between 30 and 32 g/L in survivors (each p < 0.001)." (PMID 41245629, 2025). "Patients with hypoalbuminemia had lower mean Hb levels than those with normal albumin levels (p < 0.001) and lower preoperative creatinine levels (p = 0.021)." (PMID 41488107, 2025). "25.7% of patients with normal albumin levels, 20% with mild, and 20.8% with moderate hypoalbuminemia were reoperated within the stated timeframe." (PMID 39906535, 2025). "The gender distribution was similar between the two groups, with 57 (56.4%) males and 44 (43.6%) females in the hypoalbuminemia group, and 43 (53.1%) males and 38 (46.9%) females in the normal albumin group (p=0.652)." (PMID 40161084, 2025). "ALB is a visual and straightforward indicator to evaluate the status of hypoalbuminemia and nutrition." (PMID 39775544, 2025). "Hypoalbuminemia is common in many inflammatory diseases because increased capillary permeability can lead to the leakage of albumin into the interstitial space." (PMID 40143356, 2025). "Variables were selected a priori based on clinical relevance and significant intergroup differences, including creatinine, urea nitrogen, PH, albumin, hypoalbuminemia, high pSOFA score, and high PELOD-2 score." (PMID 41322235, 2025). "At the time of listing for deceased-donor LT, laboratory tests showed jaundice (total bilirubin 6.5 mg/dL), coagulopathy (prothrombin time-international normalized ratio 1.4), hypoalbuminemia (albumin 2.1g/dL), and renal failure (creatinine 5.38 mg/dL)." (PMID 40937155, 2025). "One recent study reported that 53.1% of adult trauma patients exhibited early-onset hypoalbuminemia (albumin < 3.5 g/dL) within the first week after injury." (PMID 41226896, 2025). "Serum albumin was analyzed both as a continuous and categorical variable (hypoalbuminemia < 3.5 g/dL, normal albumin > 3.5 g/dL)." (PMID 41228270, 2025). "Hypoalbuminemia, defined as serum albumin levels below 35 g/L, is common in patients with conditions such as nephrotic syndrome, cirrhosis, or sepsis." (PMID 40051558, 2025). "RAR, which combines RDW and serum albumin, comprehensively reflects two pathological states: hematopoietic dysfunction and hypoalbuminemia." (PMID 40636366, 2025). "Inflammatory conditions enhance vascular permeability, leading to albumin leakage and subsequent hypoalbuminemia." (PMID 40777182, 2025). "Within the first 6 months, 11 (64.7%) out of 17 patients had severe hypoalbuminemia, 55 (29.1%) out of 189 patients had mild hypoalbuminemia, and 1 (4.76%) out of 21 patients who presented with normal albumin levels died." (PMID 41303773, 2025). "In the absence of definitive guidelines, our findings encourage obstetricians to measure albumin levels and treat hypoalbuminemia appropriately." (PMID 40529137, 2025). "In two randomized controlled studies, albumin was administered intravenously in a large proportion of patients to avoid hypoalbuminemia." (PMID 41303814, 2025). "Participants with hypoalbuminemia were significantly older (74.25 ± 4.01 years) compared to those with normal albumin (72.97 ± 4.13 years; p = 0.013)." (PMID 41536828, 2025). "Because albumin is mainly synthesized in the liver, cirrhotic patients exhibit hypoalbuminemia and reduction in colloid osmotic pressure, consequently developing ascites." (PMID 41149065, 2025). "Hypoalbuminemia exerts a significant influence on highly albumin-bound (>90%) and predominantly renal eliminated antibiotics, such as ceftriaxone and ertapenem." (PMID 40417688, 2025).
Hypoalbuminemia (continued). "A meta-analysis on the albumin intervention for hypoalbuminemia in patients with acute illness demonstrated a survival benefit in the albumin group when the albumin levels exceeded 3 g/dL." (PMID 40649163, 2025). "Outcomes were also assessed by albumin category, defined as normal (≥35 g/L), mild (31-34 g/L), moderate (25-30 g/L) and severe (<25g/L) hypoalbuminemia." (PMID 41431585, 2025). "Decreased production of albumin by the liver (e.g., liver damage) or increased escape of circulating albumin from the vascular space (increased vascular permeability) can lead to hypoalbuminemia." (PMID 41159750, 2025). "Patients with normal albumin levels (≥32 g/L) had a one-year HRAE-free survival of 85.7% compared with 68.5% in the hypoalbuminemia group (<32 g/L; log-rank p = 0.03)." (PMID 40943953, 2025). "Mortality was significantly higher in the hypoalbuminemia group, with a rate of 11.9% compared to 3.7% in the normal albumin group (p=0.046), indicating a statistically significant association between hypoalbuminemia and increased mortality risk." (PMID 40161084, 2025). "In the present study, patients with hypoalbuminemia had a 4-fold higher incidence of OHE than those with normal albumin levels." (PMID 40928524, 2025). "Patients with hypoalbuminemia (serum albumin < 3.5 g/dL) displayed markedly higher urinary microalbumin levels and ACRs compared to those with typical serum albumin." (PMID 41536368, 2025). "Nevertheless, the patient demonstrated only a partial and transient response, with an ongoing need for frequent intravenous albumin infusions to manage persistent hypoalbuminemia and recurrent edema, underscoring a suboptimal therapeutic effect." (PMID 41562995, 2025). "Patients who died were more likely to have had hypoalbuminemia, with 41% having had albumin levels < 3 mg/dL compared to 20% of patients who survived." (PMID 41305391, 2025). "This mechanistic framework explains the inverse relation between albumin and inflammatory activity and the frequent hypoalbuminemia in active RA observed clinically." (PMID 41346979, 2025). "In the context of an inflammatory state, hypoalbuminemia can occur because of several mechanisms related to the altered synthesis and metabolism of albumin." (PMID 39857389, 2025). "The mean preoperative serum albumin was 3.63 g/dL (SD = 0.642) and 40% had hypoalbuminemia, while 60% had normal albumin levels." (PMID 41228270, 2025). "The research conducted on patients with hypoalbuminemia showed a decreased total concentration of theophylline in blood in comparison to patients with normal albumin levels." (PMID 40051558, 2025). "In the 3–6 years age group, significantly lower albumin values were observed compared to other groups (p = 0.003), and hypoalbuminemia was more frequent in children younger than six years (p = 0.001)." (PMID 40731771, 2025). "Biochemistry revealed mild hypoalbuminemia (2.5 g/dL), severe hyperglobulinemia (6.8 g/dL) with an albumin-to-globulin ratio of 0.4, mildly elevated AST (61 U/L), and moderate hypercholesterolemia (149 mg/dL)." (PMID 40430745, 2025). "Given the limitations of conventional AG in the context of hypoalbuminemia, the albumin-corrected anion gap (ACAG) provides a more accurate reflection of acid–base disturbances." (PMID 41264595, 2025). "In particular, we focused on preeclampsia, in which oxidative stress is closely involved in the pathogenesis, and renal dysfunction leads to increased albumin excretion into the urine, resulting in hypoalbuminemia." (PMID 39857389, 2025). "Non-survivors exhibited markedly lower levels of total protein and albumin, indicating hypoalbuminemia and impaired liver function." (PMID 41440513, 2025). "In our study, the risk of 30-day mortality was higher in the patients with sepsis with hypoalbuminemia in the albumin infusion group than in the control group." (PMID 40649163, 2025).
Hypoalbuminemia (continued). "The ascites and hypoalbuminemia observed among patients with higher IL-6 likely reflect the effect of IL-6 on the liver, promoting acute phase reactants while decreasing albumin production." (PMID 40646134, 2025). "The mean serum albumin concentration was 3.30±0.62 g/dL, with 42% (n=42) of the group exhibiting hypoalbuminemia." (PMID 41536368, 2025). "Prior reviews and meta-analyses have repeatedly examined the role of albumin in patients with hypoalbuminaemia and diuretic resistance, yet they have consistently arrived at low-certainty conclusions." (PMID 41281089, 2025). "Hypoalbuminemia was also a significant predictor, with an HR of 5.18 (95% CI: 1.28–20.8, p = 0.016), indicating that patients with lower albumin levels had poorer survival." (PMID 40646134, 2025). "In cirrhotic patients, hypoalbuminemia results from decreased albumin synthesis and catabolic enhancement due to structural changes in the albumin molecule." (PMID 41008815, 2025). "Hypoalbuminemia (serum albumin <3.5 g/dL) was present in 76% (n=76) of patients, with 65% (n=65) having a severe deficiency (<2.5 g/dL)." (PMID 41426748, 2025). "In our sample, hypoalbuminemia affected 42% (n=42) of participants, aligning with earlier accounts of lowered serum albumin in cardiovascular cases." (PMID 41536368, 2025). "Panhypoproteinemia was present in 14% (10/71), hypoalbuminemia with normal total proteins in 4% (3/71) and hypoproteinemia with normal albumin in 4% (3/71)." (PMID 40326642, 2025). "The fracture-induced trauma triggers an inflammatory response that reduces serum albumin levels, leading to hypoalbuminemia." (PMID 41270055, 2025). "Albumin was evaluated as a continuous variable in 18% of studies and as a dichotomous variable in 76%, with 3.5 g/dL being the most common threshold for hypoalbuminemia." (PMID 40103850, 2025). "Laboratory tests revealed marked hypogammaglobulinemia (IgG 193 mg/dL) and hypoalbuminemia (albumin 1.9 g/dL)." (PMID 40792275, 2025). "Initial workup revealed hypoalbuminemia (albumin 23.4 g/L), hypocalcemia (calcium 1.79 mmol/L), with unremarkable urinalysis, tumor markers, BNP, viral panel, and chest-abdominal CT." (PMID 41041446, 2025). "Nevertheless, prospective validation is warranted to confirm its utility in guiding targeted therapies (e.g., granulocyte colony-stimulating factor in neutropenic sepsis or albumin supplementation in hypoalbuminemia)." (PMID 40766844, 2025). "Laboratory tests revealed severe hypoalbuminemia (albumin 1.2 g/dL) and elevated carbohydrate antigen 19-9 levels, while his renal and hepatic functions were preserved, excluding other common etiologies of hypoalbuminemia." (PMID 41497708, 2025). "Specifically, modifiable factors (e.g., hypoalbuminemia, anemia) should be addressed through nutritional support—such as albumin supplementation and iron therapy—to enhance tissue healing capacity." (PMID 41230442, 2025). "Albumin is a major heparin-binding protein; hypoalbuminemia can reduce heparin bioavailability, necessitating higher doses to achieve therapeutic anticoagulation." (PMID 41470090, 2025). "In this study, all the cases with dietary transition as the only therapeutic choice had normal total protein and albumin levels, while those with hypoproteinemia/hypoalbuminemia had concurrent dietary and medical adjustments." (PMID 40326642, 2025). "Our study addresses the long-standing controversy regarding the clinical importance of administering albumin to critically ill patients with hypoalbuminemia." (PMID 40649163, 2025). "The heightened urinary excretion of albumin, the protein component of urine, is a consequence of renal glomerular and tubular damage in women with preeclampsia, leading to hypoalbuminemia." (PMID 39857389, 2025). "In a recent study, blood profiles revealed mild anemia, lymphopenia, thrombocytopenia, hypoalbuminemia, hyperglobulinemia, and an albumin to globulin ratio of 0.4 in FIP cases." (PMID 41142566, 2025).
Hypoalbuminemia (continued). "Amongst studies that evaluated albumin as a dichotomous variable, 33% (4516 of 13.733) of patients across all studies were defined as having hypoalbuminemia based on respective study predefined cutoff values." (PMID 40103850, 2025). "Hypoalbuminemia, typically defined as serum albumin ≤3.5 g/dL, is common at dialysis initiation and is a strong predictor of hospitalization and mortality." (PMID 41552166, 2025). "A total of 182 patients were analyzed, with 101 having hypoalbuminemia (serum albumin<35 g/L) and 81 having normal albumin levels (serum albumin≥35 g/L)." (PMID 40161084, 2025). "Despite albumin infusion, diuretics, and anti-infective therapy, hypoalbuminemia persisted, though hypocalcemia was corrected after albumin supplementation." (PMID 41041446, 2025). "In such cases, the administration of human albumin has been considered to counteract hypoalbuminemia and potentially improve diuretic response." (PMID 40279952, 2025). "Our results suggest that the optimal preoperative albumin level (45.3 g/L) for predicting postoperative pneumonia is higher than the clinical cutoff criteria for hypoalbuminemia (<35 g/L)." (PMID 41200138, 2025). "Our findings indicated a significant decrease in preoperative albumin levels among patients with MDRO VAP, confirming that hypoalbuminemia is an independent risk factor for MDRO VAP after cardiac valvular surgery." (PMID 40248251, 2025). "Hypoalbuminemia has been established as an independent prognostic factor for AKI, with lower albumin levels associated with poorer outcomes." (PMID 40745462, 2025). "Albumin and high-quality protein should be supplemented to correct hypoalbuminemia, along with trace elements such as zinc and selenium to enhance lymphocyte function." (PMID 41164372, 2025). "In this study, the majority of patients in the ENFI group had hypoalbuminemia (ALB ≤ 35 g/L), and multivariate analysis confirmed that low albumin was an independent risk factor for ENFI, with an odds ratio (OR) of 2.450 (p = 0.009)." (PMID 41049372, 2025). "For hypoalbuminemia (serum albumin < 38 g/L), weighted univariable and multivariable analyses indicated that each 1-point increase in DI-GM score was associated with a significant reduction in the odds of hypoalbuminemia across all models." (PMID 40396178, 2025). "Concurrently, hypoalbuminemia may exacerbate the effects of hypovolemia: low albumin decreases plasma oncotic pressure, promoting further fluid loss into interstitial spaces and impairing circulatory volume—thus compounding hypoperfusion and raising the lactate/albumin ratio." (PMID 40944081, 2025). "The aim of this review is to assess the effect of hypoalbuminemia on the pharmacokinetics of selected drug classes in patients with low serum albumin concentration." (PMID 40051558, 2025). "The results showed that the median serum albumin was 4.0 g/dl, and hypoalbuminemia was present in 12% of the patients (<3.5 g/dl)." (PMID 40104144, 2025). "As an indicator for nutrition status, the serum albumin level was noted in 20/23 patients, with 3 of them (15%) having hypoalbuminemia." (PMID 40095606, 2025). "Patients with preoperative hypoalbuminemia (<3.5 g/dL) had a mean hospital stay of 10.1 ± 2.9 days, while those with normal serum albumin levels (≥3.5 g/dL) had a shorter mean duration of 6.9 ± 2.0 days." (PMID 40698225, 2025). "The extensive cutaneous inflammation leads to the extravasation of albumin and albumin-bound calcium into the interstitial space, resulting in hypoalbuminemia and subsequent hypocalcemia." (PMID 40291321, 2025). "Blood and ascitic fluid investigations revealed hypoalbuminemia (serum albumin 23 g/L) with ascitic albumin of 19 g/L, giving a serum-ascites albumin gradient (SAAG) of 4, suggestive of a non-portal hypertensive cause, possibly malignant." (PMID 41147025, 2025). "The findings were similar when the analysis was repeated in patients with hypoalbuminemia (albumin level <30 g/L) (eTable 4 in Supplement 1)." (PMID 39836424, 2025).
Hypoalbuminemia (continued). "During six cycles of treatment, serum albumin levels decreased from 4.3 g/dL to 3.5-3.6 g/dL (grade 1 hypoalbuminemia)." (PMID 41283603, 2025). "As the primary site of ALB synthesis, hepatic dysfunction attenuates ALB production, which often results in hypoalbuminemia." (PMID 41424785, 2025). "In adults, the normal reference range for serum albumin is between 3.5 and 5.0 g/dL, with values below 3.5 g/dL classified as hypoalbuminemia." (PMID 40283046, 2025). "Particular attention should focus on the albumin-lymphocyte-neutrophil axis: how hypoalbuminemia potentiates lymphocyte apoptosis via redox imbalance, and how neutrophilia induces NETosis that further depletes lymphocytes." (PMID 40969605, 2025). "Pro-inflammatory cytokines like IL-6 promote the production of acute-phase proteins while suppressing albumin synthesis, leading to hypoalbuminemia." (PMID 41012833, 2025). "In patients with chronic renal failure undergoing peritoneal dialysis, correction of hypoalbuminemia through albumin administration was shown to reduce platelet aggregation." (PMID 40678773, 2025). "These included albumin infusions to manage hypoalbuminemia and anasarca, a packed cell volume transfusion to treat anemia, and anticonvulsants for the management of a post-focal seizure." (PMID 40230775, 2025). "NS is a clinical condition whose most important manifestations are excessive loss of protein in the urine (proteinuria), swelling, and low levels of albumin in the blood, i.e., hypoalbuminemia." (PMID 40868160, 2025). "In our study, serum albumin levels were significantly lower in patients with >25% lung damage (p = 0.021), supporting previous data suggesting that hypoalbuminemia is a potential marker of poor prognosis." (PMID 40428888, 2025). "Twelve patients (63.1%) had hemoglobin <130 mg/dL, and 6 patients (31.55%) had hypoalbuminemia (albumin <35 mg/dL)." (PMID 40322374, 2025). "The most notable observation was the dynamic albumin change over time: initial hypoalbuminemia was common, but after aggressive care in the ICU, most patients became hyperalbuminemic." (PMID 41226896, 2025). "Of these, both parameters were normal in 55% (11/20), 30% (6/20) had hypoproteinemia and hypoalbuminemia, and 15% (3/20) had hypoproteinemia with normal albumin." (PMID 40326642, 2025). "Inthe setting of hypoalbuminemia, serum albumin, another component of BAR, has beenlinked in the past to the prognosis of various CVD." (PMID 40776939, 2025). "Hypoalbuminemia is frequently linked to an increased risk of mortality and complications with NAFLD because low albumin levels indicate systemic inflammation and poor liver synthesis." (PMID 39996009, 2025). "We mainly examined overall mortality and the risks of shock, septic shock, cardiogenic shock, hypovolemic shock, heart failure, and pulmonary edema in patients with sepsis with hypoalbuminemia following albumin supplementation." (PMID 40649163, 2025). "The timing of initiating treatment was determined depending on the serum albumin level, because hypoalbuminemia is considered an important factor in the classification of disease severity." (PMID 40895886, 2025). "During the second operation, the patient had mild anemia and hypoalbuminemia (hemoglobin 97 g/L, total protein 58.4 g/L, albumin 29.5 g/L)." (PMID 41574361, 2025). "In compiling a comprehensive summary of literature evaluating the prognostic utility of hypoalbuminemia in spinal metastasis patients, our aim was to provide greater insight into the current utilization of serum albumin in this population." (PMID 40103850, 2025). "His laboratory data revealed severe hypoalbuminemia (serum albumin, 1.2 g/dL; total protein, 3.8 g/dL), mild anemia (Hb, 10.2 g/dL), and elevated CRP (7.3 mg/dL)." (PMID 41497708, 2025). "In comparison to women during pregnancy with hypoalbuminemia, subjects with greater ALB concentrations possessed higher gestational weight gain, longer duration of gestation and lower parity (all P < 0.05)." (PMID 40233027, 2025).